APP (amyloid beta precursor protein)
Diseases named in the same sentence as APP in open-access papers (continued):
Sharing a sentence is not in itself a finding about the gene and the disease.
amyloid (continued). "Finally, recent studies of transgenic mice that co-express mutant forms of amyloid precursor protein (APP) and tau have demonstrated that oligomeric Aβ accumulation, but not total amyloid plaque burden, correlates with neuronal loss and inflammatory response." (PMID 24587111, 2014). "Additionally, robust inhibition of eIF2α phosphorylation did not block Aβ-dependent APP elevation in primary neurons, nor did it reduce amyloid pathology in 5XFAD mice." (PMID 24992504, 2014). "Additionally, p-eIF2α reduction did not block Aβ-dependent APP elevation in primary neurons, nor did it decrease Aβ levels or amyloid plaque pathology in 5XFAD brain." (PMID 24992504, 2014). "Moreover, reduction of the amyloid pathology upon chronic treatment (37 days) was detected only in the brain of 4- to 5-month-old but not of 12-month-old APP/PS1 mice, in which abundant Aβ deposits were still present." (PMID 24399967, 2013). "Observations in APP(xPS1) transgenic mice somewhat dispute this belief: atrophy can be observed before the onset of brain amyloidosis or can concurrently be absent despite a heavy local amyloid burden." (PMID 20953404, 2010). "In addition, at the age of 4.5 months APP-SAA mice likely do not have CAA-like amyloid deposits, therefore this paradigm might not be suitable for the detection of chronic anti-Aβ antibody treatment effect on microbleeds." (PMID 40830489, 2025). "Interestingly, in contrast to the positive impact of early GA treatment, our results showed that APP/PS1 mice following GA injections in a pre-symptomatic stage of amyloid-deposition did not exhibit any beneficial effect on either cognitive performance or plaque load." (PMID 38352237, 2024). "As spatial memory impairments in APP/PS1 mice primarily relate to amyloid burden and considering previous studies suggesting that A2AR might regulate Aβ production and pathology, we then characterized hippocampal amyloid pathology in APP/PS1 A2A versus APP/PS1 mice." (PMID 38964748, 2024). "Current amyloid models offer no way to direct transgenic APP to specific cell types for studies that might need this specificity, such as a comparison of APP processing in excitatory versus inhibitory neurons, or assessment of amyloid formation by layer 2/3 versus layer 5 pyramidal neurons." (PMID 35394029, 2022). "When raised germ-free, APP/PS1 mice exhibited significantly reduced amyloidosis and microgliosis, suggesting that in absence of the gut microbiota, AD pathologies are less severe and supports the hypothesis that the gut microbiota plays a critical role in AD pathologies." (PMID 33153085, 2020). "Finally, previous work genetically manipulating apoA-I levels in APP/PS1 mice found changes specifically in vascular amyloid deposition without any changes to parenchymal plaques suggesting that the cerebrovasculature is the most sensitive target of HDL in the brain." (PMID 31084613, 2019). "However, we have previously reported that Tg2576 mice, overexpressing APP, do not secrete more exosomes than their littermate controls at an age when amyloid pathology has fully developed, suggesting that AD neuropathology is not causing higher exosome secretion." (PMID 28851452, 2017). "In contrast, brain atrophy was not seen in 9.5 months old APOE4 mice with 5xFAD or APP/PS1 background, when significant amyloid burden was present at this age." (PMID 38462606, 2024). "More importantly, PB/PAMAM nanoparticles showed to reduce amyloid plaque number, rescue neuronal function, and improve spatial learning and memory in APP/PS1 mice compared to nontreated APP/PS1 mice." (PMID 37111540, 2023). "Age-associated restoration of Treg function in old mice had a marked effect in reducing the inflammatory phenotype of APP/PS1 mice brain, but were not strong enough to reduce amyloid plaque or reactive microglia." (PMID 38023614, 2023).
amyloid (continued). "Overall, the analyses showed shorter, thicker PAS coverage styles in APP/PS1 mice relative to WT mice that were appreciated among vessels both with and without amyloid, as assessed by MeX04 label." (PMID 35794106, 2022). "In amyloidosis animal models of AD, BBB disruption is observed in mouse models such as arcAβ and APP/PS1 but not prevalent in certain mouse lines such as the PS2APP line." (PMID 34832961, 2021). "In the study, both heterozygous and homozygous CH24H KO remarkably extended the life-span of APP/PS1-Tg mice, while not affecting the amyloid pathology." (PMID 33051477, 2020). "Although APP/PS1 transgenic mice do not recapitulate all aspects of AD pathology, they do undergo amyloid pathogenesis." (PMID 31903114, 2020). "To evaluate how the “rescue effect” observed in mice lacking APOE correlated with the level of amyloid pathology, we performed a stereological analysis of the load and density of amyloid plaques in the cortex of APP/PSEN1 and APP/PSEN1/APOEnull mice." (PMID 30760557, 2019). "In contrast to the studies supporting a role of monocytes in AD, a recent report using parabiosis experiments and staining for CD11b and CD45 suggests that monocytes do not infiltrate the brain in APP/PS1 and 5XFAD mouse models of amyloidosis." (PMID 30158892, 2018). "In this work, we have demonstrated that the 5XFAD mouse model of amyloid pathology, like other APP/PS1 and APP transgenic mice, does not develop ER stress because of overexpression of the 5XFAD transgenes or high levels of Aβ." (PMID 30315100, 2018). "We thus found that, whereas total Congo red levels of the control APP/PS1 mice and HHcy APP/PS1 mice were not different, HHcy APP/PS1 mice showed fewer parenchymal amyloid deposits and increased CAA levels relative to the control APP/PS1 mice." (PMID 24991237, 2014). "To investigate the involvement of neurovasculature in AD pathogenesis (for reviews:), we created a new AD knock-in mouse model (APP DSL) that develops progressive CAA and amyloid pathology in the absence of transgene overexpression." (PMID 25108425, 2014). "Attenuation of astrocytic activation via deletion of GFAP and vimentin in APP/PS1 mice exacerbated amyloid plaque load independent of APP processing and Aβ production, suggesting that astrocytes are important in amyloid clearance." (PMID 24490742, 2014). "Indeed, many of the mouse models for genetic AD that harbour different human APP mutations have also been shown to exhibit CAA, although the overexpression of APP alone causes no Aβ deposition in most mouse lines, and mouse app does not generate amyloid plaques." (PMID 21829488, 2011). "No amyloid deposits were observed in the brains of either 4-month-old APP/PS1 mice or WT mice at any age (date not shown), while they were clearly present in the hippocampus and cortex of 6 and 12-month-old APP/PS1 mice." (PMID 37899431, 2023). "Transcriptomics of neuronal FTase knockout in APP/PS1 mice identified mTORC1 signaling and promotion of non-amyloidogenic processing as the top contributor to the beneficial effects on cognition and amyloid pathology, possibly mediated through a reduction in Ras or Rheb signaling." (PMID 35987691, 2022). "In APP/PS1 AD model mice, amyloid plaques were spread throughout the entire cortex, while no Aβ staining could be seen in the brains of WT mice (data not shown)." (PMID 32066466, 2020). "Collectively, these data indicate that exercise-induced increases in theta -an ECG frequency associated to attention, and memory, result in improved memory in healthy mice, but not in APP/PS1 mice, a well-established model of AD-like amyloidosis and cognitive deterioration." (PMID 28542392, 2017). "Although these treatment strategies show high success rates in rodent models with amyloid precursor protein (APP) overexpression, a major confound is the lack of physiological deficits from aging and long term amyloid burden in these models, which are present in AD patients." (PMID 25999850, 2015).
amyloid (continued). "Whereas intraventricular injection of amyloid does not alter CCK mRNA levels in the hippocampus, and the number of CCK INs in CA1 (in SO) remained unchanged with intrahippocampal injection of amyloid, APP/PS1 mice feature a reduction of CB1R-expressing CCK interneurons in DG and CA1." (PMID 37841892, 2023). "Notably, 5xFAD transgenic mice are phenotypically different from APP/PS1 mice in that without forming Tau aggregates, they develop amyloid pathology early at six weeks of age and spatial memory impairment when they are about four months old, thus reflecting relatively expedited progression of AD." (PMID 36359919, 2022). "Furthermore, transgenic models like APP/PS1 and TgAPP mice provide important information on familial AD and amyloid pathology but may not fully translate to the more common sporadic, late-onset AD due to their overexpression of mutant proteins and the early-onset nature." (PMID 39201317, 2024).
Cognitive impairment (969 papers, 2005 to 2026). Abnormal cognition is characterized by deficits in thinking, reasoning, or remembering. "APP-Kla is susceptible to L-lactate modulation, which reduces Aβ pathology and cognitive impairment in AD model mice." (PMID 39744941, 2025). "Neuronal loss and pathological protein accumulation, such as APP and P‐Tau, are early hallmarks of cognitive impairment." (PMID 41431402, 2025). "For instance, tau deficiency has been shown to disrupt the trafficking of APP, also an iron export protein, to the neuronal surface, resulting in toxic iron retention, cognitive deficits, and parkinsonism-like symptoms in mice." (PMID 38733347, 2025). "APP mice had increased susceptibility to epilepsy and resulting hippocampal synaptic damage and cognitive impairment." (PMID 38388921, 2024). "Overall, our data supports that TL of brain tissues is negatively associated with Aβ load and cognitive deficits among APP/PS1 mice, but to a less extent among WT mice." (PMID 38450924, 2024). "An miR-425-deficient mouse model enhanced APP amyloidogenic processing and increased reactive gliosis, thus leading to neuroinflammation, cognitive impairment, and neuron loss by suppressing the PI3K-Akt signaling pathway." (PMID 38338859, 2024). "Previous research has shown that ligature-induced periodontitis in rats causes inflammatory responses, cognitive impairments, and abnormal APP processing, with STAT3 pathway activation contributing to inflammation." (PMID 39822781, 2024). "Our recent study showed that ceftriaxone played a role in improving cognitive disorders, maintaining homeostasis glutamate as a neurotransmitter, and ameliorating synapse loss in the APP/PS1 mouse model of AD." (PMID 38320997, 2024). "Altogether, our results revealed that inhibition of neutrophil infiltration by serum improved cognitive impairment, partially by alleviating synaptic loss and neuroinflammation in the hippocampus of the APP/PS1 brain." (PMID 37280283, 2023). "Young (4–6-month-old) mice carrying amyloid precursor protein (APP) mutations—an autosomal dominant cause of AD—have increased cognitive impairments and hippocampal delta-FosB levels, leading to downregulation of cFos." (PMID 36732588, 2023). "Previous studies indicate that ELS increases the susceptibility to AD by aggravating cognitive deficits and AD pathology in 6- and 12-month-old APP/PS1 mice." (PMID 37980670, 2023). "Of note, to demonstrate that the decrease in Nrf2 plays a role in the cognitive deficits associated with AD, a genetic approach to remove the Nrf2 gene from APP/PS1 mice, a widely used animal model of AD, was developed." (PMID 36978879, 2023). "The abnormally intensive APP synthesis in these mice causes the deposition of Aβ plagues in their brains and eventual cognitive impairments." (PMID 37760778, 2023). "Manganese-induced cognitive impairment is caused by dysregulated APP expression and -secretase processing of APP." (PMID 38173557, 2023). "We discovered that ZDHHC21 p.T209S contributed to AD by enhancing the palmitoylation of FYN and APP, resulting in AD pathology and synaptic dysfunction, ultimately causing cognitive impairment." (PMID 37365538, 2023). "Aβ, which is currently considered to cause cognitive impairment in AD, is mainly produced by APP in lipid rafts, and the size of lipid rafts is affected by the cholesterol concentration within neurons." (PMID 37629027, 2023). "APPSwe mouse (also known as Tg2576) is one of the most widely used mouse models of AD that overexpresses human amyloid precursor protein (APP) containing Swedish mutation and shows a cognitive impairment as early as 6 months of age." (PMID 36359919, 2022). "APP/PS1 transgenic mice express a mutated fusion of human presenilin (DeltaE9) and human amyloid precursor protein (AppSwe), leading to cognitive impairment." (PMID 35281906, 2022).
Cognitive impairment (continued). "In a study by Yujie Cheng, the oral administration of BCP prevented cognitive impairment in APP/PS1 mice, and this positive cognitive effect was associated with reduced β-amyloid burden in both hippocampus and cerebral cortex." (PMID 35296033, 2022). "In line with this, haplodeficiency of FTase specifically in APP/PS1 mice rescued cognitive impairment, while deficiency of FTase or GGTase both reduced Aβ deposition." (PMID 35987691, 2022). "The intrahippocampal injection of ASC specks in APP/PS1 mice induces the spread of Aβ deposits, while ASC deficiency inhibits the spread of Aβ and ameliorated cognitive deficits in APP/PS1 mice." (PMID 36699095, 2022). "Next, we investigated the mechanisms underlying such accelerated progression of cognitive deficits in APP/PS1-DM-RH mice." (PMID 35077394, 2022). "This leads to the reduction in the APP processing and effectively saves cognitive impairment and neuronal loss." (PMID 36213283, 2022). "GDC0575 also reverses AD-like cognitive deficits and prevents neuron loss and synaptic impairments in APP/PS1 mice." (PMID 35286657, 2022). "In this body of work, we were able to show that overexpression of wild-type human APP in mice (hAPPwt) causes early cognitive impairment, neuronal loss, and electrophysiological abnormalities in the absence of amyloid plaques and at very low levels of Aβ." (PMID 34475508, 2021). "A miR‐425‐deficient mouse model has enhanced APP amyloidogenic processing, neuroinflammation, neuron loss, and cognitive impairment." (PMID 34510683, 2021). "Here, we report that microglia-specific miR-146a overexpression reduced learning and memory cognitive deficits and ameliorated plaque-associated neuritic pathology and neuronal loss in APP/PS1 transgenic mice (APP/PS1 Tg mice)." (PMID 33754051, 2021). "Most APP-based models usually display plaque-associated dystrophic pathology, loss of synaptic-related proteins, and cognitive deficits, although some results have been contradictory." (PMID 34803589, 2021). "On the other hand, IL-10 overexpression mediated by adeno-associated virus exacerbates Aβ pathology and cognitive impairment in TgCRND8 mice, another mouse model that overexpresses mutant human APP." (PMID 33847763, 2021). "In summary, our study shows that SZRD can alleviate cognitive impairment by reducing neuronal loss and synaptic damage in APP/PS1 transgenic mice." (PMID 33478552, 2021). "Metformin treatment was shown to inhibit neuronal loss, the direct cause of cognitive deficits in AD, by promoting neurogenesis and inhibiting pathological neuronal apoptosis in the hippocampus of amyloid precursor protein/presenilin-1 (APP/PS1) mice." (PMID 35153733, 2021). "Another study with mice overexpressing a mutant form of the human APP revealed that CCH by bilateral common carotid artery surgery increased cerebral Aβ accumulation and promoted cognitive impairment in combination with APP gene mutations." (PMID 32982937, 2020). "We here demonstrate that Aβ-induced hyperexcitability of hippocampal PV interneurons plays a causal role in the early cognitive deficits observed in APP/PS1 mice." (PMID 31431685, 2020). "Compound 11 inhibited the δ-secretase enzymatic activity, reduced the concentration of δ-secretase-cleaved tau and APP fragments, ameliorated synaptic loss and electrophysiological dysfunction, and reversed cognitive deficits." (PMID 31911834, 2020). "Mild cognitive impairment has been associated with lower levels of total Tau and APP and a higher ratio of pTau-T181/total Tau in comparison to controls." (PMID 33362690, 2020). "Preventing cognitive decline with VX-765 suggests that mutant APP expression in J20 mice causes cognitive impairment via Casp1-mediated inflammation." (PMID 32917871, 2020). "We found that HF rTMS significantly rescues the learning, memory, and cognitive impairment, and reduces the neuropathology associated with AD in APP/PS1 mice." (PMID 32592331, 2020).